CSF1R (colony stimulating factor 1 receptor)
Diseases named in the same sentence as CSF1R in open-access papers (continued):
Sharing a sentence is not in itself a finding about the gene and the disease.
Sepsis (9 papers, 2013 to 2025). Sepsis is defined as life-threatening organ dysfunction caused by a dysregulated host response to infection. "Even after using additional statistical analysis, we were able to observe a decrease in PD-L1 expression on CSF1R+ monocytes in the treated sepsis group." (PMID 37261908, 2023). "High-dose application of the colony stimulating factor 1 receptor (CSF1R) inhibitor PLX5622 (1200 ppm) seven days prior to sepsis induction lead to 70–80% microglia reduction but resulted in fatal outcome of bacterial sepsis or LPS induced inflammation." (PMID 38041192, 2023). "We therefore tested partial microglia depletion using a low-dose of PLX5622 (300 ppm) for seven days prior to sepsis which resulted in an increased survival in comparison to littermates subjected to high-dose CSF1R inhibiton and to a stable microglia reduction of ~ 40%." (PMID 38041192, 2023). "Finally, the percentage of CSF1R– neutrophils slightly increased during sepsis, especially in the anti–miR-93-5p–treated group compared with the control group (P < 0.05), while the percentage of CSF1R+ neutrophils did not change between groups." (PMID 37261908, 2023). "Four genes of them were differential expressed among sepsis-alone group, sepsis-induced ARDS group and controls, which were CSF1R, HLA-DRA, IRF8 and MPEG1." (PMID 37443002, 2023). "A six-gene panel including EOMES, LTF, CSF1R, HLA-DRA, IRF8 and MPEG1 was discovered and validated with a high accuracy both in sepsis subjects and sepsis-induced ARDS subjects." (PMID 37443002, 2023). "Some selected genes were significantly higher expressed in sepsis as compared with MBC samples (CD24, CD177, MMP8, and TLR5), and in MBC compared with sepsis (HLA-DRA, CSF1R, and AGAP6/9)." (PMID 32958605, 2020). "Among these hub genes, colony stimulating factor 1 receptor (CSF1R), a cytokine which controls the production, differentiation, and function of macrophages, was significantly up-regulated in sepsis-alone group and sepsis-induced ARDS group." (PMID 37443002, 2023). "Interestingly, we also observed a chronic microgliosis as a long-term consequence of sepsis, which was not occurring in animals treated with the CSF1R inhibitor." (PMID 38041192, 2023).
breast tumor (8 papers, 2010 to 2023). "Metastasis and TAM infiltration of spontaneous MMTV-PyMT breast tumors are delayed in CSF1R-deficient op/op mice, providing the first evidence for the effect of CSF1R on TAMs200." (PMID 32801364, 2020). "We recently showed that TGF-β is the microenvironmental factor that initiates an autocrine invasion phenotype for human breast tumor cells by upregulating the expression of the colony-stimulating factor-1 receptor (CSF1R) in the MDA-MB-231 breast tumor cells in vivo." (PMID 23113900, 2012). "In addition, recent studies showed that invasion by a human breast tumor cell line is dependent on paracrine signaling with host macrophages as well as autocrine signaling involving CSF-1R expressed on tumor cells themselves." (PMID 21049007, 2010).
lung fibrosis (8 papers, 2019 to 2025). "Our report indicates that pharmacological activation of SHP-1 ameliorates pulmonary fibrosis via suppression of CSF1R signaling in macrophages, reduction of pathogenic macrophages, and the inhibition of fibroblast-to-myofibroblast transition." (PMID 37291088, 2023). "The inhibition of the CSF-1/CSF-1R signaling pathway offers a novel therapeutic modality for mitigating radiation-induced pulmonary fibrosis." (PMID 40007537, 2025). "In mouse model of bleomycin-induced pulmonary fibrosis, knocking out CSF-1 or usage of CSF-1R inhibitor showed protective effect." (PMID 40007537, 2025). "Herein, we provide a comprehensive review of the CSF-1/CSF-1R signaling pathway in radiotherapy, with a focus on advances in macrophage-targeted strategies in the treatment of cancer and pulmonary fibrosis." (PMID 40007537, 2025). "As an essential factor for macrophage differentiation and proliferation, the inhibition of CSF-1/CSF-1R pathway affects macrophage production and thus attenuates lung fibrosis." (PMID 40007537, 2025). "Caspase inhibition prevents the development of bleomycin-induced lung fibrosis in mice, suggesting an alternative to CSF1R blockade and other strategies aiming to modulate tissue macrophage activity in various pathological settings." (PMID 36835566, 2023). "Axatilimab, a humanized antibody against macrophage colony-stimulating factor receptor (CSF-1R), is in an active phase II clinical trial to dampen pulmonary fibrosis in cGVHD." (PMID 36258935, 2022). "The evidence of CSF-1/CSF-1R signaling pathway in radiation-induced pulmonary fibrosis is limited." (PMID 40007537, 2025). "Therefore, exploring the physiological and pathological roles of CSF-1/CSF-1R signal transduction in tumor treatment and radiation-induced pulmonary fibrosis is of great significance for the comprehensive treatment of malignant tumors." (PMID 40007537, 2025). "In a mouse model of asbestos-induced pulmonary fibrosis, CSF-1 monoclonal antibodies or inhibitor PLX3397 were used to block the CSF-1/CSF-1R signaling pathway to reduce monocyte differentiated alveolar macrophages and the alleviated pulmonary fibrosis was observed." (PMID 40007537, 2025). "Blocking the CSF-1/CSF-1R signaling pathway may be a potential therapeutic target for pulmonary fibrosis." (PMID 40007537, 2025). "In addition, cumulative evidence demonstrated that M2 phenotype macrophage is dominant in tissue fibrosis and the inhibition of CSF-1/CSF-1R signaling pathway ameliorated pulmonary fibrosis, including radiation-induced lung fibrosis." (PMID 40007537, 2025). "In the radiation-mediated pulmonary fibrosis model, investigators showed that activated IMs were able to induce myofibroblastic activation and ECM production via CSF1R activation, as treatment with the CSF1R mAb reversed the phenotype." (PMID 36232756, 2022). "They found that using clodrosomes to deplete alveolar macrophages did not improve pulmonary fibrosis while using CSF-1R monoclonal antibodies to deplete pulmonary interstitial macrophages alleviated radiation-induced pulmonary fibrosis." (PMID 40007537, 2025). "Our results suggest that the SHP-1 agonist SC-43, via targeting the CSF1R/STAT3/NFκB pathway in the alveolar macrophages, may hold great potential in pulmonary fibrosis resolution for IPF patients." (PMID 37291088, 2023). "Nintedanib blocks the polarization of both M1 and M2 human macrophages and markers that contribute to lung fibrosis (IL-1β, IL-8, IL-10, and CXCL13) by altering colony-stimulating factor 1 (CSF1) receptor (CSF1R) activation and its downstream PI3K/Akt signaling pathway." (PMID 36232756, 2022). "Nonetheless, the expression of CSF1R, MRC1, and FN1 exhibited a significant reduction following SC-43 treatment, implying that SC-43 may inhibit the CSF1R/STAT3 signaling pathway and diminish the expression of fibrotic genes within macrophages in vivo during the pulmonary fibrosis progression." (PMID 37291088, 2023).
meningioma (8 papers, 2022 to 2025). A generally slow growing tumor attached to the dura mater. "The T cells in meningioma showed five additional drug-target kinases that were significantly increased in expression compared to VS (CSF1R, LYN, ABL, MAP2K1, and BRAF), whereas VS had only one drug-target kinase, KDR." (PMID 41437121, 2025). "In their study, the authors reported that treatment of murine meningiomas using anti-CSF1/CSF1R monoclonal antibodies, in contrast to anti-PD1 therapy, was efficacious and inhibited tumor growth." (PMID 39273576, 2024). "Lastly, CSF-1/CSF-1R signaling has also been targeted as a therapy in high-grade meningiomas to reduce the activity of M2 phenotype immunosuppressive macrophages." (PMID 36768342, 2023). "Taken together, elucidating the direct effect of CSF1R signaling on meningioma cells could provide new insights for the development of more effective anticancer strategies for meningioma treatment." (PMID 40052125, 2025). "Although CSF1R-targeting therapies are beginning to shed light on how macrophage phenotypes are influenced by signaling pathways, the specific role of CSF1R-mediated signaling in meningiomas remains inadequately explored." (PMID 40052125, 2025). "In 2021, Yeung and colleagues were the first to examine a macrophage-targeting approach in an immune-competent syngeneic mouse model of meningioma using anti-CSF1/CSF1R immunotherapy, which has been shown to induce anti-tumoral responses in other brain malignancies, such as glioma." (PMID 39273576, 2024). "Meningiomas frequently exhibit activation of multiple signaling pathways, including VEGFR and CSF1R." (PMID 40052125, 2025). "Therefore, new targeted drug strategies in aggressive or recurrent meningiomas require an additional understanding of the complex signaling pathways regulated by VEGFR and CSF1R." (PMID 40052125, 2025).
metastatic tumors (8 papers, 2014 to 2025). "Interestingly, the combination of anti-CSF1R and anti-PD-1 treatment further significantly inhibited metastatic tumor progression in the liver and enhanced IFN-γ+ CD8+/CD4+ and Ki67+ CD8+/CD4+ T-cell infiltration in the tumor microenvironment." (PMID 37872170, 2023). "Additionally, it was demonstrated that expression of macrophage colony-stimulating factor (M-CSF) and its receptor colony-stimulating factor-1 receptor (CSF-1R) are increased in primary tumors of patients exhibiting metastatic disease." (PMID 24772169, 2014). "In addition, CSF1R-mediated signaling has been shown to mediate osteolysis in metastatic tumors." (PMID 32801364, 2020). "Transcriptomic analyses performed on metastatic tumors from mice treated with AZD7507, another CSF1R pharmacological inhibitor, showed alterations in tumor microenvironment composition and function." (PMID 34899694, 2021). "A gradually increased CSF1R from the inner tumors to the invasive fronts to the metastatic tumors was seen, whereas a trend of a decrease in IL-10 and IFNG was noted from the inner tumors to the invasive fronts to the metastatic tumors." (PMID 37586318, 2023).
thyroid cancer (8 papers, 2013 to 2025). "Mice study showed that CSF1/CSF1R mediated TAMs recruitment in papillary thyroid cancer (PTC) and targeting CSF1/CSF1R impaired BRAF-induced thyroid cancer progression." (PMID 26875556, 2016). "In addition, in a murine model of thyroid cancer, it has been demonstrated that targeting TAMs trough inhibition of CSF-1/CSF-1R impairs BRAFV600E-induced thyroid cancer progression." (PMID 34681084, 2021). "In thyroid cancer, the expression levels of SPP1 and CSF1 are significantly up-regulated, while CSF1R inhibitor can reduce their expression, thereby inhibiting tumor cell proliferation." (PMID 37097499, 2023). "Mice were treated with doxycycline for one week to develop thyroid cancer, and the expression levels of CCL2, CSF-1, LGALS3BP, INPP5D and CCL7, together with that of the chemokine receptors CCR2 and CSF1R, were measured in cancer specimens by quantitative RT-PCR." (PMID 34299284, 2021).
triple-negative breast carcinoma (8 papers, 2021 to 2026). An invasive breast carcinoma which is negative for expression of estrogen receptor (ER), progesterone receptor (PR), and human epidermal growth factor receptor 2 (HER2). "In murine triple negative breast cancer models, Colony-Stimulating Factor-1 Receptor (CSF-1R) inhibitors reduced tumor-associated macrophage-mediated suppression and enhanced response to anti-PD-1 therapy." (PMID 40566067, 2025). "Another potential strategy is the combination of a PARPi with anti-CSF-1R, as it was shown to overcome resistance in BRCA1-deficient triple-negative breast cancer." (PMID 38236558, 2024). "A brain-permeable CSF-1R inhibitor, pexidartinib (PLX3397) was administered to mice before injection of 4T1-BR5 triple negative breast cancer cells, and significantly reduced brain metastases in young mice." (PMID 40760255, 2025).
encephalitis (7 papers, 2018 to 2025). An acute inflammatory process affecting the brain parenchyma. "With the recent development of PLX5622, a colony-stimulating factor 1 receptor (CSF1R) inhibitor that causes rapid microglia depletion, the functions of microglia in viral encephalitis have been extensively revised." (PMID 34853891, 2022). "Previously, we demonstrated that colony-stimulating factor 1 receptor (CSF1R) in PVMs was upregulated and activated in chronically SIV-infected rhesus macaques with encephalitis, correlating with SIV infection of PVMs." (PMID 39049445, 2024). "Despite other CSF1R inhibitors (i.e., PLX3397 and BLZ945) being available before PLX5622, few studies investigating viral encephalitis utilised these earlier compounds." (PMID 34853891, 2022). "CSF1R antagonism in C57BL/6J mice, which normally clear TMEV in the CNS, led to acute fatal encephalitis." (PMID 34566948, 2021). "Consequently, microglial depletion with BLZ945, a different CSF1R inhibitor, resulted in increased VSV load and spread, transforming a sublethal infection into lethal encephalitis." (PMID 34853891, 2022). "Although the therapeutic potential of CSF1R inhibitors in viral encephalitis has not been directly tested in clinical, it could provide an avenue to modulate microglial activation and reduce neuroinflammation." (PMID 41221080, 2025). "Through systematic analysis of mouse models employing colony-stimulating factor 1 receptor (CSF1R) inhibition, particularly using PLX5622 and related compounds, consistent findings have emerged that challenge traditional assumptions about neuroinflammation in viral encephalitis." (PMID 41221080, 2025). "In contrast, CSF1R antagonism in SJL/J mice, which normally develop a chronic CNS TMEV infection, did not result in acute encephalitis, but exacerbated TMEV-induced demyelination." (PMID 34566948, 2021).
Hypertension (7 papers, 2019 to 2025). The presence of chronic increased pressure in the systemic arterial system. "The observed attenuated hypertension-induced short-term memory impairment mediated by CSF-1R inhibition is a novel finding." (PMID 32863942, 2020). "Of note, several of these genes (Cx43, Myh7, CSF1R, CXCR4, and CACNA1) have been reported to be associated with AF, hypertension, inflammation, cardiac and vascular remodeling." (PMID 31191333, 2019). "Furthermore, pharmacological administration of PLX5622, a potent inhibitor of colony stimulating factor-1 receptor (CSF-1R) that is required for microglial cell survival, improved short-term memory in a rodent model of induced hypertension." (PMID 34566627, 2021). "Treatment with the CSF1R inhibitor PLX5622 partly obviated the hypertension associated impairment of short-term memory without altering the normal cognitive function of control mice." (PMID 32863942, 2020). "To investigate the roles of macrophages in hypertension-induced cardiac dysfunction, we further clustered macrophages, which expressed CD68, Adgre1, Fcgr1 and Csf1r, into 15 small populations." (PMID 38443404, 2024).
B-cell lymphoma (6 papers, 2022 to 2025). "The expression of its specific receptor, CSF-1R, was found to be highly expressed in the B-cell lymphomas." (PMID 35326399, 2022). "Taken together, our results suggest a potential cross-talk between epithelial cells expressing Vav1, that secrete CSF-1, and the lymphocytes that express CSF-1R, thus leading to the generation of B-cell lymphomas." (PMID 35326399, 2022). "It was found that there is potential crosstalk between epithelial cells of VAV1 (which secrete CSF-1) and lymphocytes expressing CSF-1R, which leads to B-cell lymphoma." (PMID 35957889, 2022). "As demonstrated by IHC of lung, liver and pancreas sections with anti-Vav1, anti-CSF-1R and anti-CSF-1 Abs, while CSF-1R is expressed in cells within the B-cell lymphoma, the ligand is expressed in the epithelial tissue where transgenic Vav1 is found." (PMID 35326399, 2022). "CSF-1 in turn activates the CSF-1R on B-cells and leads to enhancement of ERK phosphorylation and cell propagation, leading eventually to the development of B-cell lymphoma." (PMID 35326399, 2022).
Cerebral ischemia (6 papers, 2017 to 2024). Restriction of arterial blood supply to the brain associated with insufficient oxygenation to support the metabolic requirements of the tissue. "Inhibited microglia CSF1R factor is indispensable in ischemic stroke to validate the evaluation of CSF1R inhibitors in clinical trials for ischemic brain diseases." (PMID 32908485, 2020). "Using a mouse model of transient focal cerebral ischemia and reperfusion, we demonstrated that depletion of microglia via administration of the dual CSF1R/c-Kit inhibitor PLX3397 exacerbates neurodeficits and brain infarction." (PMID 28273719, 2017). "Brain ischemia elicits microglial activation and microglia survival depend on signaling through colony-stimulating factor 1 receptor (CSF1R)." (PMID 28273719, 2017). "Optimized integration of TP and Ki20227 can improve cerebral ischemia by inhibiting CSF1R signal and trigger autophagy and BDNF-Akt signaling pathways to increase dendritic spine density and synaptic protein expressions, which in turn enhances neurobehavioral function." (PMID 33192177, 2020). "However, the specific signaling molecules downstream of CSF1R participating in phagocytosis in microglia after brain ischemia, and the precise step(s) of the phagocytic process affected by CSFR1 remain to be identified." (PMID 30580383, 2019).
chronic lymphocytic leukemia (6 papers, 2015 to 2023). "Targeting macrophages using anti-CSF-1R antibody or clodrolip (clodronate encapsulated liposomes) also impaired chronic lymphocytic leukemia cell engraftment." (PMID 31370273, 2019). "CSF1R+ TAMs were less frequent in B-cell lymphocytic leukaemia and lymphoblastic B-cell lymphoma than in diffuse large B-cell lymphoma, peripheral T-cell lymphoma, angioimmunoblastic T-cell lymphoma and cHL." (PMID 26066800, 2015). "Considering the CSF1/CSF1R signaling pathway as an effective therapeutic target for depleting and reprogramming TAMs, blockade of CSF1/CSF1R signaling has been demonstrated to effectively deplete neural-like cells and control the progression of chronic lymphocytic leukemia." (PMID 36845095, 2023). "In a mouse model of chronic lymphocytic leukemia, targeting MΦs using an anti-CSF1R mAb efficiently inhibited disease progression; interestingly, the leukemic cell death was dependent on TNF-α signaling and tumor microenvironment reprogramming toward an antitumoral phenotype." (PMID 34771453, 2021). "Indeed, in B-cell CLL, CSF1R inhibition with a JAK2/FLT3 inhibitor, pacritinib was associated with significant depletion of TAMs and consequently inhibited leukemic cell survival." (PMID 31783588, 2019).
demyelinating disease (6 papers, 2023 to 2026). A broad group of disorders that affect the myelin sheaths that cover the neurons. "Depletion of microglia via administration of small molecule antagonists specific for colony stimulating factor 1 receptor (CSF1R) results in increased susceptibility to viral-induced demyelinating disease." (PMID 38879499, 2024). "Multiple studies have verified the role of the CSF-1/CSF-1R axis in the development of inflammatory and demyelinating disorders that affect the CNS." (PMID 38737586, 2024). "Since CRL is a demyelinating disease and TREM2 regulates the uptake and processing of myelin debris, it is important to understand how Trem2 deficiency affects myelin uptake and processing by Csf1r+/− phagocytes." (PMID 37626591, 2023).